HIF1A (hypoxia inducible factor 1 subunit alpha)
Diseases named in the same sentence as HIF1A in open-access papers (continued):
Sharing a sentence is not in itself a finding about the gene and the disease.
tumor (continued). "In hypoxic conditions, HIF-1α facilitates the shift of tumor cells from oxidative to glycolytic metabolism by triggering genes that encode glucose transporters and glycolytic enzymes." (PMID 38799423, 2024). "An increase in tumor oxygenation achieved through external US stimulation led to inhibition of Hypoxia-inducible factor 1—alpha (HIF-1α) expression, which further reduced VEGF transcription and mitigated tumor angiogenesis." (PMID 39438891, 2024). "Oncogenes and tumor suppressors: Some oncogenes, such as the ones seen in KRAS or MYC, help increase the level of HIF-1α, thereby contributing to tumor development." (PMID 39493156, 2024). "Following this, we performed immunohistochemical staining to assess the presence of HIF-1α proteins within our cohort, specifically examining tissue samples from both ccRCC and adjacent non-tumor tissues." (PMID 38610951, 2024). "In GC, NFKB1 and HIF1A are dysregulated and often involved in tumour growth, proliferation, tumour-promoting inflammation, chemoresistance, and cell differentiation." (PMID 39816318, 2024). "The supplemented O2 not only effectively potentiated the PDT-induced nitrosative stress-triggered cell death to prevent local recurrence of residual tumor cells, but also blocked HIF-1α signaling pathway to inhibit their distant metastasis." (PMID 38280861, 2024). "Simultaneously, miR-25 enhances tumor angiogenesis by stabilizing HIF-1a and increasing VEGF expression." (PMID 39769102, 2024). "In HCC cells and nude mice, circ-0044539 downregulation or miR-29a-3p upregulation was associated with small tumor size, PI3K-AKT-mTOR pathway inactivation, and downregulation of the key LNM factors (HIF-1α and CXCR4)." (PMID 39191749, 2024). "In the hypoxic microenvironment (HME) formed by malignant tumor cells, HIF-1α is more stable under the low pH condition of lactate formation and is not easy to be degraded, thus increasing its accumulation in cells." (PMID 39464313, 2024). "TAMs accumulate in hypoxic regions and express HIF-1α, where they regulate glycolytic genes to preferentially utilize glycolysis as a means to maintain their inflammatory phenotype, thereby promoting tumor-related inflammation." (PMID 39654883, 2024). "By contrast, the normal tissues from adjacent tumor margins exhibited more prominent vasculature (depicted in red) and less presence of HIF-1α (depicted in green) compared to the tumor tissues, which demonstrated tumor hypoxia." (PMID 38514624, 2024). "HIF-1α acts as a major player in orchestrating the expression of essential genes, which in turn promotes angiogenesis, a process that is essential for tumor cell growth and metastasis." (PMID 38542288, 2024). "Overall, the results of this study showed higher expression of cells positive for the selected TME biomarkers (FAK+, CD44+, HIF-1α+, and Ki67+) within tumor nests compared to tumor stroma in tumor resection specimens of EC patients after NRCHT+R." (PMID 38727811, 2024). "Simultaneously, the intrinsic STING-mediated activation of DC promoted hypoxia-inducible factor-1 alpha (HIF-1α)-mediated glycolysis to establish a positive feedback pathway against tumor cells." (PMID 39464876, 2024). "IHC showed that 5-HT treatment upregulated HK2 and HIF-1α expression in tumor tissues, which was reversed by PI3K inhibitor treatment." (PMID 39385213, 2024). "The tumor microenvironment (TME) is a critical source for factors like hypoxia (HIF-1α, NO), and signaling proteins derived from cells such as cancer-associated fibroblasts and macrophages (TGFβ, LCN2, IL-6, IL-1β, etc.)that influence EMT50." (PMID 39737957, 2024).
tumor (continued). "Transient glycolytic activation of peritumoral monocytes in hepatocellular carcinoma was found to induce sustained expression of carbonic anhydrase XII (CA12) on tumor-infiltrating macrophages via autocrine cytokines and the HIF1α pathway." (PMID 39516356, 2024). "In particular, HIF-1α is the main factor activated under hypoxia, which promotes pathways related to tumour progression as cell survival, invasion, angiogenesis, immunosuppression and metabolic reprogramming." (PMID 38341408, 2024). "The HIF1α signaling pathway plays a crucial role in the adaptation and progression of tumor cells in a hypoxic environment." (PMID 38957393, 2024). "Western blot analysis of tumor tissues revealed that erianin concentration-dependently reduced the protein levels of PD-L1, HIF-1α, RAS, and VEGF, exhibiting a superior inhibitory effect compared to 5-FU." (PMID 38751791, 2024). "This evidence strengthens the proposition that stress-induced adrenergic activation modulates tumor phenotype, particularly through HIF-1α and the Wnt/β-catenin pathway, thereby potentiating CSC-driven resistance to DOX." (PMID 38962320, 2024). "HIF-1α also enhances the expression of glycolytic enzymes and pro-angiogenic factors, promoting tumor progression and therapy resistance." (PMID 39682234, 2024). "A study reported exosomal Wnt4, originating from hypoxic CRC cells, triggers endothelial cell migration and proliferation in a hypoxia-inducible factor-1 alpha (HIF-1α)-dependent manner, thus stimulating angiogenesis and tumor growth." (PMID 38741166, 2024). "The mTOR inhibitor everolimus impedes glucose uptake and tumor angiogenesis by downregulating HIF-1α expression." (PMID 39610917, 2024). "This combination can decrease tumor progression by reducing the expression of hypoxic and angiogenic factors, including HIF-1α and VEGF." (PMID 39055895, 2024). "In summary, LINC00518 indirectly regulates HIF-1α, promoting tumor cell proliferation, migration, invasion, and colony formation." (PMID 39108268, 2024). "For example, HIF1α expression represents the transcriptional changes that occur in response to a chronically hypoxic tumour microenvironment whereas [18F]FMISO uptake is a direct indicator of intracellular hypoxia, both acute and chronic." (PMID 39286295, 2024). "The results showed that HIF-1α knockdown inhibited tumor growth, while HPRT1 overexpression restored it." (PMID 39343971, 2024). "HIF1α suppresses oxidative phosphorylation and stimulates glycolysis (the Warburg effect) in the tumor." (PMID 39125992, 2024). "TME and Therapeutic Challenges: The TME significantly influences the SMURF2-HIF1α pathway, primarily through HIF1α, creating a critical feedback loop essential for tumor adaptation and survival." (PMID 39697237, 2024). "The molecular mechanism underlying this idea is that by regulating the ability of HIF-1α to bind to its partner HIF-1β, PT2385 can inhibit tumor growth." (PMID 39493156, 2024). "HIF signaling also upregulates PD-L1 expression, so targeting key downstream effectors of hypoxia or HIF-1α itself has therapeutic advantages in preclinical tumor models." (PMID 38887298, 2024). "HIF‐1α actively participated in glycolysis and promoted tumour cell proliferation under hypoxia conditions." (PMID 38229475, 2024). "When the nanoparticles infiltrate the tumor core, they modulate hypoxia, leading to a reduction in HIF-1α expression." (PMID 39728157, 2024). "In assessing the role and importance of HIF-1α in tumor growth, it should also be noted that in vivo experiments have shown that there are more effective pathways of proliferation that can override the pathways associated with HIF-1α signaling." (PMID 38255884, 2024). "This inhibitory effect is accompanied by a significant downregulation of key regulators of tumor progression, including hypoxia-inducible factor-1 alpha (HIF-1α), lactate dehydrogenase A, and genes involved in the epithelial-mesenchymal transition pathway." (PMID 38978503, 2024).
tumor (continued). "HIF-1α is reportedly responsible for tumor adaptation to hypoxic microenvironments through the HIF-1 pathway and hypoxia is a hallmark of solid tumors, which regulates the pathophysiology of tumorigenesis, including proliferation, angiogenesis, and metabolism." (PMID 38609977, 2024). "Given HIF1α’s central role in these processes, it presents a promising target for therapies aimed at disrupting angiogenesis and metabolic reprogramming to slow tumor progression and enhance treatment efficacy." (PMID 39697237, 2024). "Angiogenesis, metabolic tolerance to low oxygen levels, and tumor survival are all significantly impacted by HIF-1α." (PMID 39493156, 2024). "NDRG3 promotes angiogenesis under conditions of low oxygen and high concentrations of lactate by binding to c-Raf and activating Raf-ERK signaling in tumor cells to sustain HIF1A activity required for tumorigenesis." (PMID 39529665, 2024). "SIRT1 influences apoptosis and chemoresistance through hypoxia, enhancing glycolytic metabolism and HIF-1α signaling, which sustain tumor survival against drugs like gemcitabine." (PMID 39682281, 2024). "Immunohistochemical analysis showed that both whole-brain irradiation and MIF silence resulted in downregulation of HIF-1α expression in brain metastasis, which improved intra-tumor hypoxia." (PMID 38685050, 2024). "HIF-1α is a key regulator of angiogenesis and glycolysis that supports tumor cell survival, proliferation, invasion, and metastasis." (PMID 38542288, 2024). "Deletion of c-Myc in TAMs reduced the expression of proangiogenic genes (VEGF, MMP9, and HIF1a) and reduced tumor growth in a mouse melanoma model." (PMID 39516356, 2024). "The studies also found that by interfering with the activity of HIF1α, it can inhibit the metabolic reprogramming of tumor cells and improve the sensitivity of tumors to chemotherapy drugs." (PMID 38195606, 2024). "Here, the authors show that HIF1α-controlled glycolysis is an important driver of IFNγ production in hypoxic T cells, governing anti-tumor immunity." (PMID 39477954, 2024). "The pervasive influence of HIF-1α in cancer underscores its importance as a key regulator of the hypoxic response and as a critical player in tumor biology." (PMID 39493156, 2024). "The resulting activation of HIF-1α and the corresponding transcriptional program contribute to tumor progression by both stimulating cancer cell survival and proliferation and to tumor invasiveness via the induction of EMT." (PMID 39696386, 2024). "Other studies indicate that HIF-1α acts as a tumor suppressor in clear cell RCC, with only HIF-2α exerting oncogene and pro-tumorigenic functions." (PMID 39410010, 2024). "Collectively, our results indicate TRIM1’s role in predicting prognosis and reveal how TRIM1 functions to upregulate HIF1α expression and promote tumor cell proliferation." (PMID 38769340, 2024). "For the untreated tumor, the microscopic examination of HIF1α expression revealed its cytosolic and nuclear localization." (PMID 38378689, 2024). "In terms of assessing tumor hypoxia, the R2* value was highly correlated with HIF-1α (r = 0.778, P < 0.001)." (PMID 38395884, 2024). "HSP-90 inhibition induces the misfolding and proteasomal degradation of its client proteins, reducing HIF1α levels and diminishing tumor adaptive responses to hypoxia." (PMID 39697237, 2024). "Macrophages are activated by tumor-derived lactate signaling through hypoxia-inducible factor 1α (HIF1α), leading to a tumor-promoting state that is marked by increased production of arginase 1 (Arg 1) and VEGF." (PMID 38983918, 2024). "Under hypoxia in cancer cells, HIF1α and HIF2α are upregulated, and the transcription of several low-responsive genes involved in tumor growth, angiogenesis and metastasis, as well as genes related to glucose transport and metabolism, are transcribed." (PMID 38884097, 2024).
tumor (continued). "In vivo tumor growth in tumor-bearing mice administered with KC shows an inhibition rate of almost 50%, providing that KC inhibits tumor cell proliferation by inhibiting HIF-1α expression." (PMID 39339168, 2024). "HIF-1a-mediated lactate accumulation via the glycolytic pathway promotes tumor growth and reduces NK and T cell effector functions." (PMID 38727262, 2024). "According to immunohistochemical studies, HIF-1α (mRNA and/or protein) is detected in tumor cells of colon adenomas and adenocarcinomas, with more pronounced expression observed in adenocarcinomas." (PMID 39063041, 2024). "In hypoxic tumor environments, the activation HIF-1α triggers increased VEGF expression, stimulating the formation of new blood vessels." (PMID 38538285, 2024). "HIF1α expression was dramatically higher in tumor tissues than in adjacent normal tissues, which was consistent with the results of the analyses of TCGA and GEO HNSCC databases." (PMID 38485986, 2024). "Hypoxia-inducible factor-1α (HIF-1α) is a transcription factor crucial in cellular adaptation to low oxygen levels (hypoxia), a common feature in the tumor microenvironment." (PMID 39407697, 2024). "HIF-1α can enhance glycolytic activity by regulating several glycolytic enzymes in tumor cells to convert glucose into glucose-6-phosphate." (PMID 38544822, 2024). "MUC1 can also stabilize the expression of HIF1A and increase glycolytic flux in cancer cells to reduce the sensitivity of tumor tissue to anti-tumor drugs." (PMID 38702644, 2024). "In hypoxia, ROS and HIF-1α are often highly expressed in tumor cells, which promote the metabolic reprogramming of tumor cells and induce the invasion and migration." (PMID 41550172, 2024). "At the same time, combinational therapy using HIF1α inhibitors and Treg inhibitors synergistically boosted anti-tumor immunity and decreased tumor metastasis." (PMID 38361941, 2024). "The aerobic glycolysis characteristic of tumors, known as the Warburg effect, is closely linked to the overexpression of hypoxia-inducible factor 1 alpha (HIF-1α), a pivotal regulator of tumor energy metabolism." (PMID 39691396, 2024). "In the HME, mounting evidence has indicated that HIF-1α can modulate downstream target genes to promote the proliferation of tumors as well as suppress the apoptosis of tumor cells via interacting with cofactors." (PMID 37588219, 2024). "It is well known that low oxygen levels in hypoxic tumor tissues lead to the accumulation of HIF-1α." (PMID 39124883, 2024). "Synergy with hypoxia-inducible factor 1-alpha targeting: HIF-1α can be suppressed to enhance the expression of tumor antigen and the maturation of dendritic cells." (PMID 39493156, 2024). "Subsequently, HE staining was performed to assess lymph node metastasis, and we observed that miR-5100 knockdown hindered tumor metastasis in both popliteal and inguinal lymph nodes, which was obviously promoted by HIF1α." (PMID 38485986, 2024). "The HIF1A expression was significantly higher in tumor tissues compared to normal ones (p < 0.0001)." (PMID 38928200, 2024). "The mouse subcutaneous tumor model also showed that HIF1A exhibited reduced expression level after NXPH4 knockdown." (PMID 39164641, 2024). "Su conducted a review on HIF-1α/ERR α-mediated metabolic reprogramming in EC, elucidating the various signaling pathways through which HIF-1α and ERRα regulate energy metabolism to confer resistance to heat-induced apoptosis in tumor cells." (PMID 38577616, 2024). "ABCG1 is indicated to confer tumor stemness through activating the H19/HIF‐1α/PDK1 signaling pathway to induce rapid cancer cell growth and adaption to the condition of hypoxia and insufficient energy supply." (PMID 38896016, 2024). "Recent insights have highlighted the critical role of SMURF2 in the process of ubiquitination and degradation of HIF1α under both normoxic and hypoxic conditions, a process critical for modulating tumor progression, angiogenesis, and cellular metabolism." (PMID 39697237, 2024).
tumor (continued). "The cellular response to hypoxia includes the expression of HIF-1α, and there is a correlation between the extent of tumor hypoxia and overall disease prognosis." (PMID 38339228, 2024). "The O2 generation due to the water oxidation reaction in the nanocubes and nanoframes also resulted in tumor hypoxia relief following HIF-1α antibody assay." (PMID 37543632, 2023). "In vivo studies with CCR6-deficcient GBM xenografts showed reduced vascularisation, slow tumour growth, and lower expressed levels of HIF-1α compared to control (CCR6 positive)." (PMID 37686652, 2023). "The results of western blotting and IHC were consistent, in which IGFL2‐AS1 knockdown in nude mouse tumor tissues reduced the HIF‐1α and CA9 expression, whereas IGFL2‐AS1 overexpression had the opposite results." (PMID 36537608, 2023). "YFSJ and its component quercetin can inhibit the overactivation of skeletal muscle mitophagy mediated by the abnormal activation of the Stat3/HIF-1α/BNIP3 signaling pathway induced by the tumor inflammatory microenvironment, thereby alleviating CRF." (PMID 36814560, 2023). "Hypoxia-inducible factor-1α (HIF-1α) is a hypoxia-stable transcription factor that regulates the expression of multiple target genes involved in glycolysis, mitochondrial respiration, tumor metastasis, and chemotherapy resistance." (PMID 37670948, 2023). "Here, we further demonstrated that XBP-1(S) enhances the repression of the tumor-suppressive miR-34a by HIF-1A." (PMID 36831485, 2023). "Significant increase and activity of HIF-1α occurred in the tumor hypoxic microenvironment is a crucial force to trigger angiogenesis." (PMID 37111603, 2023). "Collectively, our results demonstrate that fructose promotes VEGF expression by affecting ROS and HIF1α in tumor cells, which in turn contributes to tumor angiogenesis." (PMID 37507736, 2023). "When analyzing the SCC samples, strong nuclear HIF-1α staining was present in most of the tumor cells, while only some cells showed exclusively cytoplasmatic staining." (PMID 37445752, 2023). "The results of the present study have shown that the majority (69%) of the patients with ccRCC had significantly higher levels of HIF-1α in kidney than in tumor tissue." (PMID 38273861, 2023). "Increased expression of HIF-1α and/or HIF-2α has been associated with increased tumor aggressiveness and poor prognosis in a broad range of tumor types." (PMID 37490147, 2023). "Overexpression of HIF-1α is an important factor for tumours metabolic adaptation against hypervascularization and hypoxia." (PMID 37841777, 2023). "Hypoxia-inducible factor 1 alpha (HIF-1α) is a transcription factor that regulates the cellular response to hypoxia and is upregulated in all types of solid tumor, leading to tumor angiogenesis, growth, and resistance to therapy." (PMID 37345074, 2023). "Collectively, SHMT2 reduction inhibited HIF1α expression in the tumor tissue, reduced tumor malignancy, and slowed tumor cell proliferation in vivo." (PMID 37108312, 2023). "In HIF-1α KD tumors, i.p. administration of PA + LC remarkably inhibited tumor growth and induced the strongest levels of apoptosis and fat peroxidation in KD tumors among all treatments analyzed." (PMID 38066600, 2023). "PKM2 facilitates tumor growth and promotes tumor angiogenesis by regulating HIF-1α through NF-κB activation, which ultimately triggers VEGF-A secretion and subsequent blood vessel formation." (PMID 37686525, 2023).